LRRC9 (leucine rich repeat containing 9)
Synonyms: FLJ46156
Tractability: Antibody: the Human Protein Atlas places it where antibodies can reach. PROTAC: ubiquitination databases record sites on it.
Gene: Protein-coding gene on chromosome 14 (59,919,713 to 60,066,817, forward strand). Ensembl gene ENSG00000131951.
Subcellular location (Human Protein Atlas): Cell Junctions; Plasma membrane; Nuclear bodies; Nucleoplasm
Gene Ontology:
Cellular component: cytoplasm
Homologues: Orthologues: macaque LRRC9 (97% identical), chimpanzee LRRC9 (94% identical), pig LRRC9 (86% identical), dog LRRC9 (86% identical), rabbit LRRC9 (83% identical), rat Lrrc9 (80% identical), mouse Lrrc9 (80% identical), guinea pig LRRC9 (79% identical), tropical clawed frog lrrc9 (55% identical), zebrafish lrrc9 (17% identical), Drosophila melanogaster Ppr-Y (6% identical), Drosophila melanogaster TbCMF46 (5% identical). Paralogues in human: LRRCC1 (12% identical), LRRC49 (9% identical), LRGUK (9% identical), CEP97 (9% identical), DNAAF1 (7% identical), DRC3 (7% identical), LRRC43 (7% identical), LRRIQ3 (6% identical), DNAAF11 (6% identical), PPP1R42 (5% identical), LRRC46 (4% identical), LRRC61 (4% identical), and 1 more.
Diseases named in the same sentence as LRRC9 in open-access papers:
LRRC9 is named in the same sentence as 3 diseases in open-access papers, as found by Europe PMC text mining. Sharing a sentence is not in itself a finding about the gene and the disease. The quoted sentences say what the papers report.
pancreatic cancer (2 papers, 2021). "A Kaplan–Meier survival analysis (Protein Atlas) shows that LRRC9 mRNA expression is positively correlated with survival among patients with pancreatic cancer (p = 0.0034), although the gene is not classified as prognostic." (PMID 33854844, 2021). "Furthermore, LRRC9-ART has been characterized at the expression level, and is predicted to interact with ZFP36L2, an RNA-binding protein that controls the cell cycle and is involved in pancreatic cancer." (PMID 34639169, 2021).
neuroblastoma (1 paper, 2019). Neuroblastoma (NB) is the most common solid, extracranial childhood tumor. "Overall, we found that downregulation of 7 genes (Crb1, Lrrc9, Rcn1, Rtl1, Shisa3, Six6, St18) and upregulation of 2 genes (C1ql3, Slc18A1), are strongly predictive of favorable neuroblastoma outcome, consistent with delayed tumor development in Th-MYCN/Casp2−/− mice." (PMID 30670683, 2019).
LRRC9 also shares sentences with these, for which no sentence is quoted: tumor (1 paper).